CD4 (CD4 molecule)
Diseases named in the same sentence as CD4 in open-access papers (continued):
Sharing a sentence is not in itself a finding about the gene and the disease.
lung cancer (continued). "Immune indexes CD3+, CD4+, CD8+, and CD4+/CD8+ in the lung tissue of normally fed rats and lung carcinoma model rats were detected." (PMID 34399782, 2021). "Compared with lung carcinoma model rats, CD3+, CD4+, and CD4+/CD8+ of IDO inhibitor rats were elevated, while CD8+ was declined (P < 0.05)." (PMID 34399782, 2021). "Later studies showed that anti-CTLA-4 treatment induces a robust increase in both CD4+ and CD8+ T cell populations in several human cancers including lung cancer, thereby limiting T reg infiltration into the tumor bed and increasing T effector to T reg ratio." (PMID 32117295, 2020). "Both CD4+ and CD8+ PTCAs were detected more frequently in lung cancer patients than in healthy volunteers." (PMID 32776968, 2020). "Meanwhile, human DCs co-cultured with lent-miR-138-5p-treated-human lung cancer cells had a stronger ability to induce CD8+ T cell killing of human lung cancer cells and promote CD4+ T cells proliferation." (PMID 32754587, 2020). "Given the importance of interactions with adaptive immune cells during carcinogenesis, we assessed the ability of the G-baToN system to track the interaction of primary human CD4 and CD8 T cells with lung cancer cells." (PMID 33025906, 2020). "αGFP-expressing CD4 and CD8 T cells that interacted with sGFP-expressing lung cancer cells in culture were specifically labeled." (PMID 33025906, 2020). "Targeting of IL‐17A derived from Th17 cells is beneficial in experimental lung cancer by inhibiting lung tumor‐infiltrating T regulatory cells and inducing IFN‐γ‐producing CD4+ T cells in the presence of T‐bet." (PMID 31903715, 2020). "Changes in immune parameters such as CD4+, CD8+ T-cells, NK, and myeloid derived suppressor cell populations have been suggested to be biomarkers for lung cancer and non-Hodgkin’s lymphoma treatment responses." (PMID 32560243, 2020). "We use this approach to extract TCR repertoires from RNA-Seq data obtained from sorted tumor-infiltrating CD4+ and CD8+ T cells in an HKP1 (KrasG12Dp53−/−) syngeneic mouse model of lung cancer after anti-PD-1 treatment." (PMID 32411589, 2020). "The second data set was generated in an analogous manner using eight lung cancer samples and IHC images stained for CD8+ and CD4+ T cells." (PMID 31126321, 2019). "The combination of tanshinone IIA with cyclophosphamide increases CD4+ T cell, CD4+/CD8+ T cell and NK cell populations compared to single treatment in NSCLC Lewis-bearing mice, so it can improve the immunological function in lung cancer." (PMID 31719837, 2019). "Six immune cell types (B cells, CD4+ T cells, CD8+ T cells, neutrophils, macrophages, and DCs) were assessed by TIMER against TCGA lung cancer datasets." (PMID 31816603, 2019). "They further showed that DC-based HHP lung cancer vaccine generated from monocytes of NSCLC patients induces tumor-antigen specific CD8+ and CD4+ T cells." (PMID 31555582, 2019). "In lung cancer, it has been suggested that TIL-B cells help to generate potent, long-term immune responses against cancer by presenting tumor antigens to CD4 TILs33 and their presence is correlated with improved survival." (PMID 30992440, 2019). "Over the past decade, the increase of regulatory CD4+CD25+Foxp3+ Treg cells has been noticed in tumor-infiltrating lymphocytes from ovarian cancer and lung cancer." (PMID 31796037, 2019). "We report for the first time the differential expression of checkpoint molecules on CD4+ and CD8+ lymphocytes at a different stage of activation in the local environment of lung cancer." (PMID 31010080, 2019). "In conclusion, 0.05 μg·kg− 1·h− 1 naloxone increased the number of NK cells, CD4+/CD8+ T cell ratio and the analgesic effects after thoracoscopic resection of lung cancer on PCIA, meanwhile reduced analgesics dose and PONV after the operation." (PMID 31856760, 2019).
lung cancer (continued). "The CD4/CD8 ratio was still higher in sarcoidosis than lung cancer even when we compared patients whose ages were 60–80 years (sarcoidosis 9.31 ± 4.15, lung cancer 1.70 ± 1.34, mean ± SD) (p < 0.03, Mann-Whitney U-test)." (PMID 30452447, 2018). "We prepared single cell suspensions from EBUS-TBNA samples of mediastinal lymph nodes from patients with sarcoidosis or lung cancer and analyzed surface markers (CD3, CD4, CD8, CD19, CD25) and FoxP3 expression in the resultant lymphocytes using flow cytometry." (PMID 30452447, 2018). "The correlation between abundance of TAR RNA loaded circulating exosomes and viral load/CD4+ T-cell counts can be critical in determining progression of certain NADCs, such as HNSCC and lung cancer." (PMID 30389917, 2018). "When compared with lung cancer lymph node metastasis, the CD4/CD8 ratio was significantly higher in sarcoidosis, whereas the CD3/CD19 ratio was significantly higher in lung cancer." (PMID 30452447, 2018). "In the EAM overexpression group, CD8 T-cell score was high whereas activated CD4 and CD8 T-cell infiltration was low in both types of lung cancers." (PMID 29348685, 2018). "We initially analyzed the proportion of TIL T cell subsets based on CD4 and CD8 expression in a discovery cohort of 21 RCC, 16 lung cancer and 16 CRC samples." (PMID 30534127, 2018). "Lung cancer patients expressed significantly decreased proportions of naïve CD4+ T cells, naïve CD8+ T cells, CD4+ naïve/memory ratios, and CD4+CD45RA+CD45RO+ T cells and increased memory CD4+ T cells compared to healthy controls." (PMID 29137371, 2017). "DC-based HHP lung cancer vaccine generated from PBMCs of NSCLC patients stimulated significantly higher amount of IFN-γ-producing CD8+ and CD4+ T cells than DC stimulated with poly(I:C) alone or iDC." (PMID 28187172, 2017). "This study aimed to explore the relationship between age, increase in CD4+CD25+FOXP3+ Treg and the high incidence of lung cancer in the elderly." (PMID 28253320, 2017). "The analysis of basic T lymphocyte markers, CD4 and CD8, was shown to be useful in the prognosis for survival in lung cancer after surgery." (PMID 28831395, 2017). "We further evaluated the number of both CD4+ and CD8+ tumor-infiltrating lymphocytes from representative mice in each group that developed lung cancer." (PMID 29137294, 2017). "Our experiment confirmed that, within the same age group, the proportion of CD4+CD25+FOXP3+/CD4+ T cells and the expression level of FOXP3 mRNA in the peripheral blood were significantly higher in lung cancer patients than in healthy controls." (PMID 28253320, 2017). "We further examine if DC-based HHP lung cancer vaccine induces proliferation and IFN-γ-production in CD8+ and CD4+ T cells." (PMID 28187172, 2017). "Most importantly, we observed that DC-based HHP lung cancer vaccine stimulates proliferation and IFN-γ production in CD8+ and CD4+ T cells and lowers the numbers of CD4+CD25+Foxp3+ T regulatory cells in vitro." (PMID 28187172, 2017). "To assess the distribution of the CD4+ and CD8+ T cell subsets in human lung cancer, we analyzed the Tn, Tcm, Tem, and Teff of the PBMCs from the healthy donors and NSCLC patients by flow cytometry according to established surface markers." (PMID 28101811, 2017). "The distinct distribution of CD4+ and CD8+ T cell in TILs results in different clinical outcomes in lung cancer patients." (PMID 28101811, 2017). "DC-based HHP lung cancer vaccine stimulated significantly higher number of IFN-γ-producing CD8+ and CD4+ T cells in comparison to iDC or DC pulsed with HHP-killed tumor cells alone." (PMID 28187172, 2017). "The levels of CD4+CD25+FOXP3+/CD4+ T cells and FOXP3 mRNA were significantly higher in lung cancer patients than in healthy controls (t = 7.16, P < 0.01 and t = 3.65, P < 0.01, respectively)." (PMID 28253320, 2017).
lung cancer (continued). "For example, decreased proportions of CD4+ cells (T helper cells), CD4/CD8 ratios, and B cells and increased CD8+CD28- T lymphocytes and regulatory T (Treg) cells were observed in patients with lung cancer." (PMID 28624781, 2017). "Tumor samples from three lung cancer patients were analysed by flow cytometry, staining for CD19, CD3, CD4, CD8, Foxp3, TNFR2, GITR and OX40." (PMID 27626702, 2016). "We investigated which cells were involved in BaP-induced lung cancer by analyzing cell surface markers in the tumor microenvironment using antibodies against CD45, CD19, CD4, and CD68." (PMID 26565418, 2015). "The frequency of peripheral Tregs (CD4+CD25+CD127−) in CD4+T cells and frequency of naïve Tregs (CD45RA+CD4+CD25+CD127−) in CD4+T cells from lung cancer patients was significantly lower than in the healthy (P <0.05)." (PMID 25381811, 2014). "Frequencis of CD4+T cells and CD19+B cells in PBMCs from patients with lung cancer significantly decreased as compared with healthy individuals (P <0.001, respectively)." (PMID 25381811, 2014). "In our lung cancer patient group, we have found that TIM-3 was expressed on average at about 30% of the CD4+ TILs and CD8+ TILs." (PMID 22363469, 2012). "TIM-3 is highly upregulated on both CD4+ and CD8+ TILs from human lung cancer tissues but negligibly expressed on T cells from patients' peripheral blood." (PMID 22363469, 2012). "Nadir CD4 cell count in the HIV patients diagnosed with lung cancer was 110 cells/μL (IQR; 45 cells/μL - 230 cells/μL) and median CD4 cell count at time of cancer diagnosis was 299 cells/μL (IQR; 130 cells/μL - 521 cells/μL)." (PMID 21702995, 2011). "In lung cancer patients ANOVA showed a time effect for cortisol, melatonin, TSH, CD4, CD16, CD25, TcRδ1 and IL2." (PMID 20565977, 2010). "SFXN1 has been implicated in mitochondrial iron metabolism and immune response modulation in other cancer types, such as lung cancer, but this study expands its importance to immune infiltration in HNSC, particularly highlighting its link with CD4+ T cells and possible impact on clinical outcomes." (PMID 41399448, 2026). "Furthermore, the gene set of highly expressed GZMA CD4 T cell showed a better overall survival rate in lung cancer patients, further supporting the anti-tumor function of GZMA CD4 T cells." (PMID 40959273, 2025). "The results of three lung cancer-related clinical trials showed that artesunate combined with chemotherapy upregulated the CD39, CD279, and GrzB expression in CD8+ and CD4+ T cells in patients with lung cancer, thereby modulating the immune function of T-cell subsets." (PMID 41347152, 2025). "Using scRNA-seq data from 27 lung cancer patients, we identified expression levels of SIRPG in different cell subtypes and found SIRPG was mainly expressed in T cells, especially CD8+ Tex and CD4+ Tregs." (PMID 38833156, 2024). "A clinical study investigating PG2 plus gefitinib therapy for advanced lung cancer showed markedly higher serum CD3+, CD4+, and CD4+/CD8+ cell counts in the observation group than in the control group after treatment, accompanied by a better QOL (higher KPS scores) and fewer toxic and side effects." (PMID 38515577, 2024). "Indeed, we observed high expression of ENPP1 in exosomes from breast and lung cancer tissue samples, and tumor exosomal ENPP1 inhibited the immune infiltration of CD8+ T cells and CD4+ T cells." (PMID 38498770, 2024). "Regular monitoring of CD4+ T cell levels and the CD4+/CD8+ T cell ratios in peripheral blood could become a critical strategy for guiding treatment decisions in lung cancer patients, whether they receive radiotherapy or immunotherapy." (PMID 39483483, 2024). "Furthermore, high expression of ENPP1 in exosomes is observed isolated from human breast and lung cancer tissue, and tumor exosomal ENPP1 inhibited the immune infiltration of CD8+ T cells and CD4+ T cells." (PMID 38498770, 2024).
lung cancer (continued). "In our study, IFN was inhibited in CD4+, CD8+, and CD56+ lymphocytes in the presence of oncoproteins E6 and E7, and low amounts of IFN were found in the supernatants of lung cancer cells transfected with HPV oncogenes and co-cultured with lymphocytes and monocytes." (PMID 39599846, 2024). "The factor that was most strongly associated with mortality in all categories analysed (all NADC, and viral, nonviral and lung cancers), was the time-updated CD4 T-cell count." (PMID 38008809, 2023). "In contrast to the observed reduction in CD4+ T cells, the frequency of total peripheral blood NK cells did not decrease in lung cancer patients." (PMID 36901716, 2023). "After culture, significant increases in the number of GzB expressing cells gated on CD3+, CD4+, CD8 + and NKCD8 + T cells in the PBMCs from lung cancer patients before induction of chemotherapy as compared to control individuals as well as patients during and after induction of chemotherapy." (PMID 37580655, 2023). "Moreover, non-CD8+ PBMCs, containing NKs, macrophages, DCs, and CD4+ T cells, exhibited lower A549-stimulated CXCL10 expression in a patient with lung cancer compared to a healthy volunteer after co-cultured with A549 for 24 h." (PMID 36688994, 2023). "Although the role of CD4+ NKT cells is not established in lung cancer, these cells show no cytotoxic activity against tumor cells." (PMID 37377611, 2023). "Also in lung cancer, isolated TIL-B cells were found to induce CD4+ T cell expansion in response to tumor lysate or cancer-testis antigen." (PMID 37868967, 2023). "High expression of the BC-specific ICD-derived metagene signature (TNF/CXCR3/P2RX7/CASP1/NLRP3/IL1B/LY96/CD4+/CD8+A/CD8+B/PRF1/IFNG/IL17A/IL17RA) is associated with prolonged overall survival (OS) in BC and OC patients but not in lung cancer patients." (PMID 37445860, 2023). "In conclusion, our study shows that ablative SBRT leads to transient lymphodepletion but a significant increase in the fraction of proliferating CD4+ and CD8+ circulating T-cells after treatment in lung metastatic disease, consistent with our findings in primary lung cancer." (PMID 38014120, 2023). "Hence, the balance of CD4+ T and CD8+ T cells is pivotal for lung cancer prognosis, and morphine-induced tumor immune escape was further supported." (PMID 36476246, 2022). "Our IF-IHC results of LLC allograft in mouse and tumor specimens from lung cancer patients demonstrated a strong expression of CHI3L1 in macrophages, CD4+ T cells and CD8+ T cells, suggesting that macrophages and T cells are an important source of CHI3L1 in tumors." (PMID 34987649, 2022). "Few blood-derived CD4+ T cells expressed CD137 in healthy controls and lung cancer patients." (PMID 35197968, 2022). "To further confirm this result, we used antibodies to delete CD8+ (Fig EV5A–C) or CD4+ (Fig EV5D and E) T cells in our TD lung cancer transgenic mice and found that the therapeutic effect of Carfilzomib was significantly compromised after deletion of either population (and EV5F and G)." (PMID 34898004, 2022). "Additionally, ZC3H12D expression was higher in immune cells displayed by single-cell RNA-sequencing data, especially in Treg cells of lung cancer and CD8 T cells, B cells and CD4 T cells of LUAD." (PMID 35090416, 2022). "The subjects of this study were lung cancer patients, and the results showed that the levels of CD3+, CD4+, CD4/CD8+, and NK in the four groups at T1 were lower than those at T0, which confirm that routine mechanical ventilation can adversely affect the patient's immune system." (PMID 35252340, 2022).
lung cancer (continued). "Among these, B cells, CD4+ T cells and CD8+ T cells play a central role in adaptive immunity through expression of neoantigens and HLA class I molecules on their cell surface, which enables recognition and killing of lung cancer cells." (PMID 34351868, 2021). "An intriguing finding of our studies was that MTR OralGem treatment enhanced antitumor immunity in a syngeneic lung cancer model by decreasing the percentages of CD4+Foxp3+ Treg cells and increasing CD3+CD4+ and CD3+CD8+ T effector cell infiltration in the TME." (PMID 33920884, 2021). "CD4+ Th1 cells, activated CD8+ T cells, and γδ-T cells were proved to be related to favorable prognosis of lung cancer, whereas Th2, Th17, and Foxp3+ Treg cells were proved to be related to an unfavorable prognosis of lung cancer." (PMID 34887858, 2021). "In addition, there was a significant relationship between the expression of hepcidin and the infiltration levels of B cells, CD4+ T cells, CD8+ T cells, macrophages, neutrophils, and dendritic cells in lung cancer." (PMID 33868231, 2021). "Active circulating CD4+Th cells (i.e. expressing PD-1 and TIM-3 or CD62Llow) have, for instance, been shown to correlate with a better outcome in cohorts of breast and lung cancer." (PMID 33842304, 2021). "Compared with chemo or targeting therapy alone, add-on with Aidi injection showed consistent effects on three-year survival rate (2 RCTs), progression free survival (2 RCTs), KPS scores (12 RCTs), and immune function assessed by CD4 and CD4/CD8 (10 RCTs) in lung cancer patients." (PMID 34025425, 2021). "A 16-week, 3 times a week, 60-minute low-intensity simplified 24-form Tai Chi training significantly attenuated CD55 expression but did not alter the CD4+ : CD8+ ratio in lung cancer survivors." (PMID 33777155, 2021). "We discovered that levels of NK cells, CD4+ T cells, naïve CD4+/CD4+, naïve CD4+ T cells, CD4+CD28+ T cells were significantly different in lung cancer patients versus healthy individuals and that the percentages of the different cell subsets are associated with lung cancer stage." (PMID 34488711, 2021). "Furthermore, dopamine-mediated increases in DRD1 expression have been shown to suppress the proliferation and cytotoxicity of CD4 and CD8 + T lymphocytes in lung cancer patients in vitro." (PMID 34717619, 2021). "Therefore, the prognostic value of different subtypes of CD4+ and CD8+ T cells in lung cancer were needed to be studied by more researches." (PMID 33859531, 2021). "There was a higher frequency of CD4+CD25+ T cells in patients with lung cancer and PE than in subjects with lung cancer without PE." (PMID 34925358, 2021). "There was a negative correlation between CD3+ and CD4+ cells and OS in smoking stage II female lung cancer patients (PCC = 0.626, P<0.05; PCC = 0.534, P<0.05, respectively)." (PMID 33859531, 2021). "Recently, interleukin 22 (IL22), an immune molecule secreted mostly by CD4+ T cells, was reported having functions in a variety of human diseases including encouragement of lung cancer progression, yet, its role in CM is lacking." (PMID 32201538, 2020). "We also found that all patients presented systemic CD4 T cells with mainly Th17 phenotypes, without differences between responders and progressors, and without significant differences in the percentage of lung-cancer-specific CD4 or CD8 T cells." (PMID 32033028, 2020). "These cells have been speculated to deactivate CD4 T cells and decrease the CD8+ to Treg ratio in mouse PDAC33, but have unclear role in the lung-cancer microenvironment, hence requiring further investigation." (PMID 32572028, 2020). "However, platelet-CD4+ and platelet-CD8+ T cell aggregates were each increased in lung cancer patients compared to healthy volunteers." (PMID 32776968, 2020). "In addition to flow cytometry, immunohistochemistry also showed that iNOS inhibition combined with radiation significantly increased CD4+ and CD8+ T cells in lung cancer tissues." (PMID 32226302, 2020).